IL6 (interleukin 6)
Diseases named in the same sentence as IL6 in open-access papers (continued):
Sharing a sentence is not in itself a finding about the gene and the disease.
Obesity (continued). "In individuals with overweight and obesity, the consumption of 240 mL of 100% authentic tart cherry juice for 4 weeks reduced plasma Tnfα and Mcp1 without affecting Il6 or Ill0 levels, compared to the placebo group." (PMID 39683572, 2024). "Our study revealed a significant increase in serum IL-6 levels among patients with both obesity and MASLD compared to the normal-weight group without MASLD." (PMID 38732626, 2024). "In obesity, various cellular and molecular processes induce inflammation, especially in adipose tissues, which leads to the release of inflammatory mediators like tumor necrosis factor α (TNF-α), C-reactive protein (CRP), and interleukin 6 (IL-6)." (PMID 38725575, 2024). "Moreover, adipose tissue in older adults with obesity functions as a dynamic endocrine organ, secreting an array of hormones and pro-inflammatory cytokines, like TNF-a, IL-1a, IL-6, and CRP." (PMID 38668557, 2024). "In addition, MThistle reduced IL6 gene expression in the eWAT, which correlates with visceral WAT in unhealthy obesity." (PMID 39683558, 2024). "Malnutrition weakens the immune system, reducing essential immune cells like T lymphocytes and impairing antibody production, while overnutrition and obesity result in chronic low-grade inflammation, elevating inflammatory markers such as C-reactive protein (CRP) and interleukin-6 (IL-6)." (PMID 39201314, 2024). "For instance, adipose tissue in obesity generates and releases an increased amount of pro-inflammatory adipokines, including tumor necrosis factor- alpha (TNF-α), interleukin-6 (IL-6), and leptin, which results in skin inflammation and is associated with psoriasis." (PMID 38550599, 2024). "Similarly, in pregnant mice with obesity, there are increased levels of inflammatory markers, including TNF-α, IL-6, interleukin-1β (IL-1β), nuclear factor kappa-light-chain-enhancer of activated B cells (NFκB) and interleukin-10 (IL-10) in the placenta." (PMID 38671859, 2024). "Obesity often correlates with heightened levels of systemic pro-inflammatory markers like C-reactive protein, TNF-α, TGF-β, leptin, and IL-6, and we have shown that reducing TNF-α and TGF-β1 levels improved AHR and fibrosis in the same HFD-induced obesity model." (PMID 38762465, 2024). "Moreover, in individuals with obesity, HSCRP is significantly increased and elevated IL-6 is observed across all obesity categories." (PMID 39902244, 2024). "The study which investigated the chronic effect of IL-6 in 33 inactive adults with obesity and 27 inactive adults, respectively, reported no significant changes in IL-6 levels for both HIIT and MICT groups after 2 weeks and 10 weeks (P < 0.05)." (PMID 39416746, 2024). "Additionally, in the state of obesity, adipose tissue releases various cytokines, such as tumor necrosis factor‐α (TNF‐α) and interleukin 6 (IL‐6), which play a role in chronic inflammation." (PMID 39606808, 2024). "Obesity induces chronic low-grade inflammation, particularly in visceral fat, which releases inflammatory cytokines such as tumor necrosis factor alpha (TNF-α) and interleukin-6 (IL-6)." (PMID 39684545, 2024). "Additionally, the systemic inflammatory markers, including levels of IL-1β, IL-1RA, IL-6, and TNF-α, were comparable between the overweight/obesity and healthy weight groups, suggesting similar inflammatory profiles regardless of weight status." (PMID 39201638, 2024). "Also, TNF-α was the most examined inflammatory factor (Pro-inflammatory) in obesity and NAFLD, and IL-6 was the most explored pro-inflammatory factor in diabetes." (PMID 38504163, 2024). "We analyzed the levels of these adipokines based on BMI and identified an obesity effect on leptin and IL-6 but not adiponectin and FABP4." (PMID 39408921, 2024). "In addition, obesity promotes the transition of macrophages to the M1 phenotype, which secretes more pro-inflammatory cytokines (e.g., TNF-α, IL-6, and IL-1β)." (PMID 39831058, 2024).
Obesity (continued). "As high fat and obesity potentially drive inflammation activation, so we detected the cytokine levels in HFD-fed mice’s hearts and found that IL-1β and IL-6 production was elevated in HFD-fed mice’s hearts, suggesting inflammation as a mediator in HFD-induced cardiac dysfunction." (PMID 39007149, 2024). "Obesity resulted in a marked increase in the expression of cyclooxygenase-2 (COX-2) and IL-6 in the adipose tissue of HFD animals, with concurrent moderate increases in TNF-α, IL-17A, and IL-18, while IL-1β changes were minor and inducible nitric oxide synthase (iNOS) expression was reduced." (PMID 38672413, 2024). "Obesity was a chronic low-grade inflammatory state, which further exacerbated the inflammatory response induced by dyslipidemia by increasing circulating inflammatory factors, such as TNF-α and interleukin 6 (IL-6)." (PMID 39243068, 2024). "Inflammatory cytokines, tumor necrosis factor-α (TNFα) and interleukin-6 (IL-6), both of which produce sleepiness and fatigue, are elevated in OSA and obesity, which might lead to extensive usage of CPAP therapy." (PMID 39162731, 2024). "However, we demonstrate that obesity elevates FABP4 secretion from adipose tissue into the circulation, where extracellular FABP4 can directly target breast cancer cells, enhancing IL-6/STAT3/ALDH1-mediated tumor stemness and aggressiveness." (PMID 39054536, 2024). "Abdominal obesity is considered to be an inflammatory state, and many inflammatory factors come from visceral adipose tissue, such as IL-6, TNF-α, C-reactive protein (CRP), leptin, etc., which may lead to obesity-related airway inflammation." (PMID 38926790, 2024). "Prior reports indicate that obesity does not affect the amount of leptin or IL-6 secreted from breast AT or purified breast adipocytes." (PMID 39408921, 2024). "Once calibrated, the BCIABM was used to simulate the B-cell response to repeat antigen stimuli during states of low, chronic background inflammation, implemented as low background levels of IL-6 and TNF-α often seen in patients with conditions such as diabetes, obesity, or advanced age." (PMID 38261584, 2024). "In obesity, leptin levels are elevated and act as pro-inflammatory adipokines, inducing certain cytokines such as tumor necrosis factor-alpha (TNF-α), interleukin (IL)-1, and IL-6." (PMID 38255203, 2024). "The results indicated elevated IL-6 (interleukin 6) serum levels in individuals with obesity with MASLD compared to the normal-weight group without MASLD." (PMID 38732626, 2024). "Obesity‐induced inflammation activates various signaling pathways, impairs insulin signaling, and promotes the release of proinflammatory mediators such as TNF‐α, IL‐1β, and IL‐6, all of which contribute to IR." (PMID 38812572, 2024). "In contrast, genetic IL-6 deletion in mice provided no protection against the obesity-induced renal impairment but aggravated nephrotoxic effects of high fat diet-induced instead." (PMID 39723211, 2024). "For instance, while leptin may directly enhance cell migration, its impact could be modulated by other factors such as IL-6 or IGF-1, which are also upregulated in obesity." (PMID 39339753, 2024). "The inflammatory response observed in our study, characterized by increased intraepithelial lymphocyte infiltration and varying levels of the pro-inflammatory cytokines IL-6 and TNF-α, further underscores the role of chronic inflammation in obesity-related gut dysfunctions." (PMID 39684433, 2024). "Pro-inflammatory factors such as tumor necrosis factor-α (TNF-α), interleukin 6 (IL-6), interleukin 8 (IL-8), interleukin 18 (IL-18), interleukin 1β (IL-1β), or chemokine ligand 2 (CCL2) are also produced by WAT and are all increased in obesity." (PMID 38474344, 2024). "On the other hand, obesity did not affect the concentration of IL-6, although exercise (Ex), dietary inclusion of the nutraceutical (NT), and their combination (NT + Ex) significantly decreased this parameter." (PMID 38539808, 2024).
Obesity (continued). "Considering the link between obesity and inflammation, we aimed to examine the early effects of bariatric surgery (laparoscopic sleeve gastrectomy) on inflammatory and anti-inflammatory cytokines (TNF-α, IL-6, IL-10)." (PMID 39180618, 2024). "In mothers without obesity, Flt3L, IL-6 and TNFα expression levels were comparable between those who gave birth at term and preterm." (PMID 39627409, 2024). "Molecular markers of inflammation, such as TNF-α, IL-6, and CRP, were significantly elevated in individuals with obesity and insulin resistance, and these markers could predict the development of T2DM." (PMID 40302954, 2024). "In obesity, the release of FFA and cytokines (IL-6, IL-1β, PAI-1, TNF-α) from VAT into the portal vein may contribute to hepatic insulin resistance, hepatic triglyceride deposition, and NAFLD—the portal hypothesis." (PMID 39063184, 2024). "Proinflammatory cytokines such as IL-17, IL-6, IL-1 and TNF-α are increased in psoriasis and numerous studies suggest that they play a pivotal role in developing type 2 diabetes, hypertension, dyslipidaemia, obesity, insulin resistance and their complications." (PMID 39720714, 2024). "The obesity-related increase in VAT is characterized by the accumulation of macrophages, which are predominantly polarized M1 state and hence produce proinflammatory cytokines, including interleukin (IL)-1β, IL-6, and tumor necrosis factor-α (TNF-α)." (PMID 39201522, 2024). "Indeed, the normal circulatory increase in cytokines, such as interleukin-6 (IL-6) and tumor necrosis factor-alpha (TNF-α), during the third trimester is exacerbated in women with overweight/obesity when compared to normal-weight women." (PMID 38671859, 2024). "Obesity can induce a phenotypic shift of ATMs from M2 to M1, with pro-inflammatory cytokines such as TNF-α, interleukin (IL)-1, and IL-6, which are particularly secreted by M1 ATMs, exacerbating insulin resistance and contributing to local or systemic metabolic dysfunction." (PMID 39303983, 2024). "Fluctuations in pro-inflammatory cytokine levels in HFD-fed zebrafish, particularly IL-6 and TNF-α, mirror findings in human obesity, where gastrointestinal inflammation plays a central role in the development of functional gastrointestinal disorders such as irritable bowel syndrome." (PMID 39684433, 2024). "Macrophages are considered to be a major source of proinflammatory mediators, and levels of proinflammatory adipokines including interleukin-6 (IL-6), monocyte chemotactic protein-1 (MCP-1), and tumor necrosis factor-α (TNF-α) are elevated in obesity and are connected with IR directly." (PMID 39080624, 2024). "Adipose tissue in obesity secrets proinflammatory mediators such as TNF-α, IL-1β, and IL-6." (PMID 38317220, 2024). "However, this is the first study that correlates IL6 and VEGF in pregnancies complicated by obesity, diabetes, and preeclampsia." (PMID 38893732, 2024). "Circulating levels of the intestinal inflammatory factors CCL5 and IL-6 as well as the IL-18/IL-18BP ratio were increased (P < 0.05) in patients with obesity with and without T2D being also significantly associated with endotoxin levels." (PMID 38315242, 2024). "In addition, psoriasis is often accompanied with comorbidities such as obesity, insulin resistance, diabetes and NAFLD due to an increased levels of such proinflammatory cytokines (e.g., TNFa, IL-6 and IL-17)." (PMID 38496030, 2024). "Obesity is often characterized by a state of chronic low-grade inflammation, with the increased production of pro-inflammatory cytokines such as tumor necrosis factor-alpha (TNF-α), interleukin-6 (IL-6), and monocyte chemoattractant protein-1 (MCP-1)." (PMID 39765868, 2024). "Furthermore, adiponectin has anti-inflammatory properties, and in obesity, the secretion of pro-inflammatory cytokines such as tumor necrosis factor-alpha (TNF-α) and interleukin-6 (IL-6) increases, while adiponectin levels decrease." (PMID 39728435, 2024).
Obesity (continued). "The connection between obesity and immunity has been widely described; under conditions of excess weight, adipose tissue dysfunction promotes an increase in pro-inflammatory cytokines, such as TNF-α and IL-6." (PMID 36839394, 2023). "This indicates the presence of the obesity-related latent inflammatory process in the patients with high BMI and further promotes the production of inflammatory cytokines like TNF-α, interleukins-6 (IL-6), and IL-1 in adipose tissue." (PMID 36819139, 2023). "Of note, on the counterpart, obesity-related inflammatory status was partially reduced in the bariatric group compared to non-surgical controls, reflected by significantly lower IL-6 and higher adiponectin levels." (PMID 37432255, 2023). "Higher levels of adipokines, such as leptin, and elevated production of inflammatory cytokines, like interleukin-6 (IL-6) and tumor necrosis factor-alpha (TNF-α), in the adipose tissue of people with obesity can contribute to chronic inflammation and insulin resistance." (PMID 38023258, 2023). "IL-6 is a cytokine of which increased concentrations secreted by adipocytes and monocytes are thought to be responsible for inflammation and INS resistance in obesity." (PMID 36615169, 2023). "This influx of inflammatory immune cells into obese adipose tissue promotes the production of inflammatory cytokines such as tumor necrosis factor (TNF), interleukin-6 (IL-6), and interferon gamma (IFN-γ), which contribute to the chronic inflammatory state (metaflammation) observed in obesity." (PMID 37276236, 2023). "In the contexts of aging, obesity, stress, infections, injuries and smoking, activation of NF-κB and STAT3 in nonimmune cells triggers a positive feedback loop of the IL-6-STAT3 axis to NF-κB, which is called the IL-6 amplifier." (PMID 37449201, 2023). "Another RCT among 15 youth with obesity demonstrated increases in total adiponectin with reductions in IL-6 following a lifestyle intervention that did not induce weight loss but significantly reduced fat mass and improved insulin sensitivity." (PMID 37299403, 2023). "Second, visceral fat is also an active endocrine tissue, increased secretion of adipose-specific cytokines (e.g., leptin, IL-6, and TNF-α) in patients with obesity or abnormal adipose distribution also inhibits gonadotropin secretion, which in turn inhibits HPG axis." (PMID 38260153, 2023). "In obesity, oxidative stress, along with the release of pro-inflammatory cytokines, such as leptin, IL-6, and TNF-α from adipose tissue, can lead to NAFLD, non-alcoholic steatohepatitis, fibrosis, and liver cirrhosis progression." (PMID 37246210, 2023). "In patients with asthma, elevations of non-type-2 signals such as IL-6 correspond with higher blood neutrophil counts, obesity, a lower percent predicted FEV1, increased asthma-related hospitalizations, and increased use of systemic corticosteroids." (PMID 37901346, 2023). "Obesity induces a chronic low-grade inflammatory state, as does inflammaging, defined as age-related increases in pro-inflammatory cytokines, including TNF-α, IL-1β, and IL-6." (PMID 37681878, 2023). "Dysfunctional adipocytes resulting from obesity disrupt the equilibrium of metabolic mediators, including adiponectin, visfatin, chemerin, resistin, leptin, and inflammatory cytokines, such as tumor necrosis factor alpha (TNF-α) and interleukin-6 (IL-6)." (PMID 37794318, 2023). "For example, curcumin prevents obesity-related colorectal cancer by attenuating chronic inflammation and improving adipokine imbalance, reducing cyclooxygenase-2 (COX-2), AMPK, NF-κB, TNFα, IL-6 and leptin levels, while increasing adiponectin levels." (PMID 36670988, 2023). "In metabolically unhealthy obesity (MUO), cytokine profile changes include an increase in pro-inflammatory markers like IL-6, TNF-α, MCP-1 and high-sensitivity C-reactive protein (hs-CRP) with a concomitant decrease in anti-inflammatory markers like adiponectin." (PMID 37081489, 2023).
Obesity (continued). "On the other hand, obesity is characterized by systemic, chronic, and low-grade inflammation, with an increase in C-reactive protein (CRP), Alpha 1-acid glycoprotein (AGP), and interleukin 6 (IL-6)." (PMID 36982031, 2023). "First, we identified gene sets related to the function of each obesity-related serum factor: HG/HI (Insr, Irs1, Rps6kb1, Slc2a4, Slc2a5, Slc2a1), TNF-α (Tnfrsf1a, Tradd, Traf2, Fadd), IL-6 (Il6ra, Il6st, Jak1), and fatty acids (PA, LA, Chol; Ffar1, Ffar4, Ppara, Pdk4, Pgc1a)." (PMID 37047207, 2023). "Obesity exerts a multitude of effects both locally and systematically, through a series of inflammatory mediators (increased leptin, reduced adiponectin, TNF-α, IL-6), growth factors (insulin, IGF-1), and metabolism molecules (visfatin, grehlin, and resistin)." (PMID 37834153, 2023). "Reduced the levels of obesity-related TNF-α and IL-6, reduced fasting glucose and insulin levels." (PMID 36671814, 2023). "The main objective of this study was to verify the effects of weight loss induced by RYGB on the circulating levels of systemic inflammatory markers adiponectin, resistin, leptin, TNF-alpha, IL1-beta interleukins, IL-6, IL-8, IL-17, IL-23 and IGF-1 in women with severe obesity and MS." (PMID 36788619, 2023). "Based on previous studies, it is possible to hypothesize that the decrease in fat mass, as confirmed in this study, was a determinant of the reduction in serum levels of IL-6 and TNF-α in young women with obesity." (PMID 36976940, 2023). "For instance, leptin secreted by adipose stromal/stem cells isolated from women with obesity enhances the expression of epithelial-to-mesenchymal transition (EMT) and metastasis-related genes, such as serpine 1, matrix metalloproteinase 2 (MMP-2) and IL-6." (PMID 36670988, 2023). "In women, independent of obesity, the leptin-reducing allele increased height and decreased FPI, the cholestasis parameter gGT and the cytokine IL-6." (PMID 36833305, 2023). "In conclusion, our study introduced for the first time a negative association of IL-6 with self-esteem and a positive one of TNF-α with depression in a Greek cohort with obesity." (PMID 37529617, 2023). "However, the long-term usage of the inhibitors of mTORC1 increases interleukin-6 (IL-6) production, activates the signal transducer and activator of transcription 3 (STAT3), and facilitates HCC development in a murine obesity liver model." (PMID 36768977, 2023). "Blocking the IL-6 trans-signaling prevents macrophage infiltration in WAT during HFD-induced obesity, but does not improve insulin resistance." (PMID 38136564, 2023). "A meta-analysis has shown that obesity can alter serum levels of pro-inflammatory mediators (i.e., IL-6, CRP, TNF-a, resistin and leptin) in patients with periodontitis, while periodontitis can alter the levels of these mediators in patients with obesity, aggravating the inflammatory profile." (PMID 37798684, 2023). "In age-sex-adjusted models, a history of stroke, obesity, depressive symptoms and elevated non-HDL cholesterol and IL-6 were associated with an increased risk for brain aging 5 years later." (PMID 38455939, 2023). "The peripheral level of IL-6 is increased in obesity; however, these changes do not correspond with IL-6 levels in the brain, which, instead, are reduced." (PMID 38069238, 2023). "Obesity induces persisting low-grade inflammation because of increasing macrophage infiltration, which further activates immune cells to release proinflammatory cytokines (i.e., CRP, TNF-α, and IL-6) into the circulation." (PMID 37778442, 2023). "Leptin, adiponectin, resistin, visfatin, omentin, and inflammatory cytokines (such as tumor necrosis factor-alpha (TNF-α), interleukin-6 (IL-6), and monocyte chemoattractant protein-1 (MCP-1)) are just some of the known hormones that are released by adipocytes in both obesity and diabetes." (PMID 37441501, 2023).